RIBC2 (RIB43A domain with coiled-coils 2)
Description:
Microtubule inner protein (MIP) part of the dynein-decorated doublet microtubules (DMTs) in cilia axoneme, which is required for motile cilia beating.
Synonyms: C22orf11; DKFZp566F0546; FLJ25720; TRIB
Tractability: Small molecule: a structure with a bound ligand is known. PROTAC: ubiquitination databases record sites on it.
Gene: Protein-coding gene on chromosome 22 (45,413,693 to 45,432,509, forward strand). Ensembl gene ENSG00000128408.
Subcellular location: Cytoplasm, cytoskeleton, cilium axoneme; Cytoplasm, cytoskeleton, flagellum axoneme
Subcellular location (Human Protein Atlas): Connecting piece; End piece; Mid piece; Principal piece; Calyx; Perinuclear theca
Gene Ontology:
Molecular function: protein binding
Biological process: flagellated sperm motility
Cellular component: axonemal microtubule; nucleus; axonemal A tubule inner sheath; sperm flagellum; axoneme
Genetic constraint (gnomAD): Loss-of-function variants: 39 observed, 41.07 expected, observed/expected ratio (o/e) 0.95, 90% interval 0.73 to 1.24. The upper end of that interval is the gene's LOEUF score, 1.24, which puts it in group 5 of 6, group 1 being the genes least tolerant of losing a copy. Missense variants: 436 observed, 463.08 expected, observed/expected ratio (o/e) 0.94, 90% interval 0.87 to 1.02. Synonymous variants: 160 observed, 162.82 expected, observed/expected ratio (o/e) 0.98, 90% interval 0.86 to 1.12.
Homologues: Orthologues: chimpanzee RIBC2 (98% identical), macaque RIBC2 (89% identical), dog RIBC2 (83% identical), pig RIBC2 (82% identical), rat Ribc2 (70% identical), mouse Ribc2 (69% identical), guinea pig RIBC2 (64% identical), rabbit RIBC2 (64% identical), tropical clawed frog ribc2 (53% identical), zebrafish ribc2 (38% identical), Drosophila melanogaster CG7264 (32% identical). Paralogues in human: RIBC1 (35% identical).
Diseases named in the same sentence as RIBC2 in open-access papers:
RIBC2 is named in the same sentence as 13 diseases in open-access papers, as found by Europe PMC text mining. Sharing a sentence is not in itself a finding about the gene and the disease. The quoted sentences say what the papers report.
breast carcinoma (1 paper, 2021). "RIBC2 is abnormally expressed in renal clear cell carcinoma, breast cancer, and ovarian serous cystadenocarcinoma." (PMID 34530829, 2021).
cervical cancer (1 paper, 2025). A primary or metastatic malignant neoplasm involving the cervix. "Interestingly, two core genes, RIBC2 and MAN2A1, were further identified as key players in the onset and progression of cervical cancer." (PMID 39963268, 2025).
cervical squamous cell carcinoma (1 paper, 2021). A squamous cell carcinoma arising from the cervical epithelium. "Importantly, RIBC2 has been identified as a key gene related to the progression and prognosis of cervical squamous cell carcinoma." (PMID 34530829, 2021).
colon cancer (1 paper, 2025). "Among the QTL-linked transcripts identified, MCM3AP-AS1 and RIBC2 were consistently upregulated in colon cancer." (PMID 41219359, 2025). "By integrating these expression data with our eQTL results, we identified RIBC2 and MCM3AP-AS1 as genes that not only carried m6A-associated eQTL signals but were also significantly upregulated in colon tumors compared to normal tissues." (PMID 41219359, 2025). "RIBC2, although not previously characterized as a cancer-associated gene, also exhibited consistently elevated expression in colon cancer." (PMID 41219359, 2025). "This broader expression pattern is consistent with previous studies reporting that RIBC2 and MCM3AP-AS1 are differentially expressed and clinically relevant in various human cancers beyond colon cancer, likely through mechanisms independent of m6A regulation." (PMID 41219359, 2025).
endometrial carcinoma (1 paper, 2025). A malignant tumor arising from the epithelium that lines the cavity of the uterine body. "The result suggested that MAN2A1 and RIBC2 may act as a risk or protective factor in the occurrence, development, and prognosis of endometrial cancer." (PMID 39963268, 2025).
tumor (2 papers, 2025 to 2026). "RIBC2 expression was markedly upregulated in chronically transformed epithelial cells, established EC cell lines, and clinical tumor specimens, and its elevation was associated with unfavorable clinicopathological characteristics." (PMID 41666178, 2026). "Moreover, immune profiling indicated that high RIBC2 expression was linked to an immune-excluded tumor microenvironment, implying a potential role in modulating responsiveness to immunotherapy." (PMID 41666178, 2026). "The TCGA-UCEC dataset analysis revealed a correlation between RIBC2 expression and various clinicopathological variables, including body mass index (BMI), grade, histology, stage, and tumor burden status." (PMID 39963268, 2025).
RIBC2 also shares sentences with these, for which no sentence is quoted: cancer (2 papers); calculus (1); colon adenocarcinoma (1); esophageal cancer (1); ovarian serous cystadenocarcinoma (1); renal clear cell carcinoma (1); Stomach Adenocarcinoma (1).